CD4 (CD4 molecule)
Diseases named in the same sentence as CD4 in open-access papers (continued):
Sharing a sentence is not in itself a finding about the gene and the disease.
infection (continued). "In the present study we show that CD4+ T cells are sufficient to protect against R. typhi in the C57BL/6 RAG1-/- infection model by activating MΦ via IFNγ and other factors." (PMID 27875529, 2016). "Studying T-lymphocyte subsets in patients with severe acute respiratory syndrome (SARS) investigators found that cell count of naïve CD4+ (CD4+CD45RA+CD62L+) remarkably decreased during the 1st week after the infection." (PMID 26989331, 2016). "The dynamics predicted by the model also shows that the total CD4+ T-cell count decreases faster in the morphine group than in the control group, particularly during the acute phase of infection." (PMID 27668463, 2016). "In the period in which IDU had no access to cART, the impact of HIV/HCV on telomere length was noticeable already at the first timepoint in infection that we analysed, in both the CD4 and CD8 T-cell compartment with significantly reduced telomere lengths." (PMID 27034702, 2016). "The persistence of HIV-1 is believed to be a consequence of a population of latent proviruses that are established early during the primary infection and remain dormant for years, mostly in long-lived memory CD4+ T cells." (PMID 27484989, 2016). "Cats 165 and 186 demonstrated extremely reduced circulating CD4+ absolute counts at <200 cells/μl onward from weeks 202 and 167 post-infection respectively and nadirs of 60 and 90 cells/μl." (PMID 26741651, 2016). "The present study provides the first evidence that commensal bacteria that are altered in the colonic mucosa of untreated, viremic HIV-1 infected individuals enhance both productive infection and depletion of LP CD4 T cells by CCR5-tropic HIV-1 ex vivo." (PMID 26762145, 2016). "As a protein involved in co-stimulation, increased levels of ICAM-3 have not only been shown to increase HIV-1 transcription and viral production, but also to augment the infection of resting CD4+T cells." (PMID 27600080, 2016). "In the pathogenic HIV-R3A acute infection model, HIV-1 viral load reaches its peak around one week post infection and then significantly decreases with substantial CD4+ T cell depletion." (PMID 27608046, 2016). "To address these questions, we adoptively transferred antigen-experienced splenic YFP+ GFP− and YFP+ GFP+ CD4+ T cells, obtained on day 7 of infection, into naive congenic (CD45.1+) mice or congenic mice on day 7 of infection." (PMID 26459508, 2016). "IMPORTANCE Infection of CD4+ T cells and their role as latent reservoirs have been rigorously assessed; however, the frequency of productively infected monocytes and macrophages in vivo has not been similarly studied." (PMID 27030272, 2016). "Our previous studies demonstrated that primary E. muris infection induces the expansion and maintenance of E. muris specific central memory CD4+Th1 cells at 3–4 weeks after infection; the time points at which NK cells were depleted in the current study." (PMID 27092553, 2016). "Surprisingly, we did not observe any obvious or extensive differences in the phenotypic profiles of CD4+ YFP+ GFP+ cells obtained from the different tissue sites during infection." (PMID 26459508, 2016). "Infection of primary human CD4+ T cells with HIV-1BaL triggered the release of ProTα at 24 h post-infection (60 ng/ml in HIV-1-infected vs. 10 ng/ml in mock-infected supernatants)." (PMID 27310139, 2016). "Specifically, 30–60% of CD4+ memory T cells throughout the body were infected by SIV at the peak of infection, and most of these infected cells disappeared with 4 days." (PMID 27708644, 2016). "Secondary infection resolved in CD4-depleted μMT mice only after anti-CD4 treatment had ceased and CD4+ T cells repopulated in each animal." (PMID 27600502, 2016). "Our aim was to describe, with new clustering in-situ tools, which memory CD4+ T-cell populations that were highly activated, exhausted, and transcriptionally dysregulated in these infections." (PMID 27525551, 2016).
infection (continued). "Instead, cell-to-cell transmission though the virus synapse results in abortive infection of resting CD4+ T cells and the accumulation of reverse-transcribed HIV genomes in the cell." (PMID 27592079, 2016). "Concordant with the upregulation of GFP by CD4+YFP+GFP− T cell–derived memory CD4+ T cells during challenge infection, CD4+ T cells were the predominant source of IL-10 in both the spleen and liver on days 2 and 4 of secondary infection." (PMID 27630165, 2016). "Following infection or inflammation, we found that there was a sustained increase in number of locally persisting CD4+ T cells." (PMID 27160938, 2016). "More recently, in a S. pneumoniae mouse model of infection, CD4+ T cells exhibited significant upregulation of CD69 in the spleen." (PMID 26989699, 2016). "Our results with CCR5 antagonist TAK-779 treatment suggest the interaction of R3A-Env with CCR5 receptor contributed to CD4 T cells depletion during R3A infection." (PMID 27026376, 2016). "Infection with the ΔNF-κB2 single mutant showed a reduction in integration in CCL19-treated CD4+ T cells in only two of the 4 donors tested." (PMID 27459960, 2016). "Our model predicts a rapid decrease of the CD4 count in the morphine group compared to the control group at the beginning of the infection, consistent with the experimental data." (PMID 27668463, 2016). "The mean absolute circulating CD4+ T cell count of FIV-infected progressor cats from 0–290 weeks post infection was 774.5 cells/μl ± 709.7, while the mean for FIV-uninfected cats was 2714 cells/μl ± 965.2." (PMID 26741651, 2016). "Paradoxically, topical IFNβ also prevented infection despite increasing the frequency of CCR5+ CD4+ T cells, likely due to simultaneous upregulation of antiviral mediators." (PMID 27500281, 2016). "The characteristics of HIV infection in the patient (CD4+ T-cell nadir, peak viral load, duration of infection and viral control on c-ART) are also key determinants of CD4+ T-cell recovery." (PMID 27082982, 2016). "While several studies have convincingly shown a preferential loss of intestinal IL-17 and IL-22 producing CD4+ T-cells in HIV and SIV infection, it is unclear how exactly the functions of these cells are perturbed during infection." (PMID 26829644, 2016). "The acute phase of infection is followed by a prolonged asymptomatic phase, in which the cat remains clinically healthy despite a progressive decline in the peripheral blood CD4+ T cell numbers and leukocyte function." (PMID 26741651, 2016). "An examination of the mechanisms of immunity behind this long-term protection in PD-1KO mice showed a key role for parasite-specific CD8+ T cells even when CD4+ T cells and B cells responded to re-infection." (PMID 27217330, 2016). "CD38+ CD4+ T cells retained their cytotoxic function and impaired ability to produce cytokines throughout infection." (PMID 27662621, 2016). "The dendritic cells were also known to capture exosomes from the exosome-producer cells or infected CD4+ T cells and export to HIV-susceptible cells for the infection." (PMID 26981123, 2016). "Peak viral loads ranged between 6.1 to 7.3 log RNA copies/ml by week 2–6 and resulted in modest 6–14% declines in CD4+ T cell levels during acute infection." (PMID 26849216, 2016). "HIV-1 primary infection is characterized by a massive activation of CD4+ T cells responsible for its depletion and for the generation of the viral reservoirs that impede the eradication of the infection." (PMID 26973648, 2016). "In patients with AAV, CD4 + CD28null expansions are driven by CMV and are associated with an increased risk of infection and mortality." (PMID 27450392, 2016). "The function of blood stage antigen-specific CD4+ T cells in P. vivax patient during acute infection and after recovery from the infection has been studied widely." (PMID 26886867, 2016). "The data showed that, along with the infection, the IL-2 mRNA level of CD4+ T cells was gradually reduced compared to the uninfected cells." (PMID 27145859, 2016).
infection (continued). "We utilized the LPAC model to investigate the impact of HAMB species on LP CD4 T cell infection and depletion in vitro." (PMID 26762145, 2016). "In agreement with this, we found that CD4+YFP+GFP− T cell–derived memory cells reactivated quickly during secondary infection, proliferating and upregulating IL-10 GFP expression." (PMID 27630165, 2016). "This is consistent with the poor memory CD4+ T cell response that was observed in the spleen both after a primary infection (4 and 7 days) and secondary infection (2 and 7 days)." (PMID 27905502, 2016). "Infection of these cells differs from the infection of blood cells infected, mainly the CD4+ T-cells." (PMID 27746784, 2016). "For both vaccination and natural infection we observed broader coverage in terms of the total number of reactive residues for CD4/class II compared with CD8/class I, as well as higher overall response frequencies for class II MHC antigens." (PMID 28018746, 2016). "Nef is produced early in infection and is therefore able to affect CD4 surface levels immediately by targeting molecules already present on the cell membrane." (PMID 26950141, 2016). "The protection afforded to naive mice by immune serum is particularly notable at days 10 to 14 of the infection, a time when the numbers of CD4+ T cells in the genital tract tissue are increasing." (PMID 27600502, 2016). "Compared with the CHI group, the AHI group had shorter estimated infection time [65.0 (38.5–106.0) days vs. 631.0 (133.0–1135.0) days, p < 0.001] and higher CD4 cell counts [404.0 (281.5–531.5) cell/μl vs. 173.0 (113.3–243.2) cell/μl, p < 0.001]." (PMID 27600391, 2016). "Albeit CD4+ T cell response was engaged more rapidly (48 h after challenge), levels of cytokine production were similar to those observed after a primary infection." (PMID 27905502, 2016). "It includes HIV-1 viral dynamics, CD4+ T cell infection rates, and pharmacokinetics/pharmacodynamics modeling." (PMID 26870960, 2016). "Several important in vitro models of HIV-1 latency utilize these factors to promote survival of resting CD4 T cells in vitro and to increase their permissiveness to infection by HIV-1." (PMID 26728316, 2016). "Tat is a transcriptional transactivator of the HIV genome which favours the generation of new activated CD4+ T cell targets for infection and interacts with Env enhancing viral infectivity." (PMID 27450538, 2016). "T lymphocytes were the effectors against heterologous strain PAO-6 infection, and in vivo CD4+ T cell depletion during immunization diminished the vaccine based protection against PAO-6 infection." (PMID 26879055, 2016). "In contrast, consistent with their exhausted phenotype, the small numbers of residual primary infection–derived CD4+YFP+GFP+ T cells were relatively unresponsive during secondary infection." (PMID 27630165, 2016). "IL-15 SA treatment accentuated the CD4+ T cell activation more so than the CD8+ T cell activation in the liver after infection." (PMID 26859674, 2016). "Chez les 54 patients décédés, l’infection par le VIH était diagnostiquée depuis une durée médiane de 50 mois et le nadir des CD4 était < 50/mm3 dans 25 cas (46%)." (PMID 28292068, 2016). "ART was introduced in Uganda in 2004, but until 2011 ART was prescribed only at late stage infection (CD4 count below 250 cells/mL)." (PMID 27815945, 2016). "Both CD4+ and CD8+ T-cell homeostasis are clearly disturbed during untreated HIV infection: in the acute phase of infection, the majority of memory CD4+ T cells in the gut are lost while in the chronic phase, peripheral CD4+ T cells are gradually lost." (PMID 27010200, 2016). "In this regard, we already reported the HIV-1 entry in human podocytes is mainly mediated by DC-SIGN, a lectin-type surface receptor able to bind HIV-1 in a CD4-independent manner and promote trans-infection to CD4pos T cells." (PMID 27599995, 2016).
infection (continued). "Rapid and more-sustained elevations in IL-1ra, MIP-1α, IL-5, IL-10 and IL-17 levels were followed by IL-1β, IL-2, IL-7, IL-9, IL-12, IL-15, IFN-α2, MIP-1β, FGF-2 and GM-CSF at over 2 months post-infection, and accompanied by the recovery of CD4+ cells." (PMID 27830756, 2016). "Three weeks post-HIV infection, CD4+ T cell levels were significantly decreased in the PB compared to pre-infection levels (mean: %CD4+ T cells weeks 0 vs 3: 76.2% vs 65.5%; p = 0.001)." (PMID 27438728, 2016). "All volunteers in our CHMI study had a pre-existing proportion of CD4+ T cells expressing CD38 prior to infection, as do all healthy volunteers we have since examined." (PMID 27662621, 2016). "Splenic CD4+ YFP+ GFP+ T cells from mice on day 7 of infection were almost universally CXCR3+, whereas they expressed only low levels of CCR1, CCR6, and CXCR6." (PMID 26459508, 2016). "This showed that the absence of either IL-4Rα, or RELMα, leads to increased number of CD4+ T cells in the sdLN following repeated infection comparable to the levels seen in 1x mice." (PMID 27505056, 2016). "Protected mice received an intranasal B. pertussis challenge 56 days after the primary infection (D0) and showed increased percentages of IFNγ- and IL-17A-producing Prn-specific CD4+ CD44+ T-cells on 10 days p.c. compared to the percentage in naive mice." (PMID 27711188, 2016). "In contrast, following infection, there was a time-dependent increase in the frequency of apoptotic CD4+ T-cells in the mLN of Dectin-1−/− mice." (PMID 26349660, 2016). "On the other hand, in a P. yoelii model of infection, pDCs numbers increased by day 6 and remained high until at least day 14, and they were able to induce IL-10-expressing CD4+ T cells." (PMID 27110574, 2016). "Siglec-1 on DCs capture HIV-1 by interacting with sialyllactose-containing gangliosides exposed on viral membranes and subsequently mediate trans-infection of CD4+ T cells." (PMID 26667473, 2016). "Our results show that the GALTs, including GI LNs, have more severe declines in both CD4+ T cell percentages and the CD4/CD8 ratios than in peripheral blood at the end-stage of infection." (PMID 27708644, 2016). "The establishment of latency in vitro through direct infection of resting CD4+ T-cells is significantly enhanced by CCL19 and mDC, but the efficiency was dependent on virus titre, co-receptor usage and there was significant donor variability." (PMID 27383184, 2016). "This indicates that the infection process of resting naïve CD4+ T cells successfully progressed by cytokine stimulation immediately after spinoculation." (PMID 27990142, 2016). "The depletion of CD4+ T cells in the GI tract occurred coincidently with productive infection of large numbers of mononuclear cells at this site." (PMID 27708644, 2016). "Surprisingly, CD25+ cell-depletion prior to infection caused a shift in the immune response towards Th2, as shown by an increase in the levels of IL-13+ CD4+ T cells and a slight decrease in IFN-γ+ CD4+ T cells in the LRNs." (PMID 27175511, 2016). "All CD38+ CD4+ T cells isolated from healthy volunteers either prior to infection, or during experimental malaria infection, displayed similar features clearly distinguishing them from CD38- CD4+ T cells." (PMID 27662621, 2016). "Infection of the CD4-positive T lymphocytes leads to the depletion of this cell population during the acute phase of the disease while macrophages are identified as one of the major reservoirs of virus." (PMID 27068393, 2016). "In preventive vaccines, the help of CD4 T cells is crucial in mounting specific-antibody responses that are able to block the spread of infection." (PMID 27608046, 2016). "Mice devoid of functional CD4+ T cells died significantly more rapidly than control mice 14 days after infection." (PMID 27905502, 2016). "Mice were infected with P. murina and depleted of CD4+ T-cells every 6 days with depletion occurring prior to secondary infection (2°)." (PMID 27242785, 2016).
infection (continued). "CD8+ T cells also demonstrated significant accumulation in the spleen 2 days post-infection, in contrast to CD4+ T cells which were little changed." (PMID 27315117, 2016). "CD4+ T cell clones specific for epitopes derived from gp85 and gp350 recognised EBV-infected B cells at the earliest assay time point, 1 day post-infection; similar kinetics were seen in other experiments probing with gp110-specific CD4+ effectors." (PMID 27096949, 2016). "I am most optimistic regarding approaches that utilize engineered HIV-resistant T cells and stem cells to phenocopy a graft vs leukemia effect (i.e., to purge endogenous CD4 T cells), and to use cellular host restriction factors to block infection." (PMID 27668293, 2016). "mDCs were most potent at inducing latent and productive infection of resting CD4+ T-cells following infection with both X4 and R5-tropic HIV EGFP reporter viruses, compared to unstimulated or CCL19-treated T-cells." (PMID 27383184, 2016). "In order to assess the impact of IL-2/anti-IL-2 complex-mediated expansion of non-CD4 immune cell populations in the murine ear dermis infection model, we combined the anti-CD4-mediated reactivation of Mtb with the expansion of non-CD4 immune cell populations." (PMID 27391012, 2016). "Our results showed that the participation of CD8+ T-cells in the DLN was less evident than the involvement of CD4+ T-cells during infection with both species of the parasite." (PMID 27073297, 2016). "CD4+BrdU+ effector T cells from miR-155−/− mice 7 days post-infection significantly reduced compared to WT mice." (PMID 26931072, 2016). "Following activation and infection of CD4 T cells, cultures were maintained with the addition of only rIL-2 for 10–13 days to bring the activation state of the T cells close to baseline." (PMID 27513449, 2016). "Together these data confirm that CD4+ RTEs retain antigen specificity for L. donovani, provide good protection against infection and undergo efficient effector cell differentiation when transferred and allowed to expand in a lymphopenic environment." (PMID 27658046, 2016). "An important next step is to include the differentiation of B cells during responses and reactions occurring in different locations such as the site of infection and the germinal centers of lymph nodes as well as CD4 T cell help and affinity maturation." (PMID 27336297, 2016). "In the control cats, a significant change during the course of infection was only observed for the activated CD4+ T lymphocyte subset (pF < 0.05)." (PMID 27496124, 2016). "An effect of viral load on clonotypic composition was suggested by a strong correlation between F-MLV DNA copy numbers in the spleens of FV-infected recipients and frequency of Vα2 clonotypes in virus-specific CD4+ T cells 35 days post infection." (PMID 26728651, 2016). "During the evolution of the infection, the population of IL-4-producing CD4+ T-cells increased during the Lb infection and decreased during the La infection." (PMID 27073297, 2016). "We show that the establishment of latency in vitro through direct infection of resting CD4+ T-cells is significantly enhanced by CCL19 and mDC, but the efficiency was dependent on virus titre, co-receptor usage and there was significant donor variability." (PMID 27383184, 2016). "When compared with wild-type mice, WASp KO mice had a delayed response to L. major infection at 2 weeks post infection as evidenced by smaller lesion size and decreased CD4+ T-cell infiltration." (PMID 27425374, 2016). "In cooperation with other cell types, however, CD4+ memory T cells can provide clear protection during re-infection." (PMID 27754364, 2016). "In the T-cell compartment of dLNs, WASp KO mice had significantly lower number of CD4+ T cells both at 2 and 6 weeks post infection when compared with wild-type mice." (PMID 27425374, 2016).